APP (amyloid beta precursor protein)
Diseases named in the same sentence as APP in open-access papers (continued):
Sharing a sentence is not in itself a finding about the gene and the disease.
scrapie (7 papers, 2012 to 2024). A fatal disease of the nervous system in sheep and goats, characterized by pruritus, debility, and locomotor incoordination. "The overexpression of APP in other genetic expression profiling studies in scrapie murine models has been previously reported." (PMID 22897917, 2012). "As exosomes represent a mechanism of information transfer among neurons, a possible drawback could be the transmission of pathological proteins, such as the scrapie form of the prion protein (PrPsc), amyloid precursor protein (APP) fragments, phosphorylated tau or alpha-synuclein." (PMID 24705158, 2013). "In addition, the overexpression of APP facilitates the rapid development of artificial scrapie." (PMID 22897917, 2012). "Transcript levels of C3 and Saa3 were significantly lower in brain tissue from APP/PS1 x C/EBPD(-/-) mice and scrapie-infected C/EBPD(-/-) mice compared to the respective controls." (PMID 26230261, 2015).
vascular dementia (7 papers, 2014 to 2025). A degenerative vascular disorder affecting the brain. "Among these variants, APP p.L364F and PSEN1 p.R54X were found in vascular dementia cases with AAO ranges of 56–60 years and 41–45 years, respectively." (PMID 40813364, 2025). "Among these variants, APP p.L364F and PSEN1 p.R54X were found in vascular dementia cases with AAO ranges of 41–45 years and 46–50 years, respectively." (PMID 39606324, 2024). "Furthermore, two carriers of APP variants were considered controls at the moment of inclusion: control 3 carried the APP p.S198P variant and CSF analysis did not reveal Aβ alterations; control 4, carrying the APP p.R328W and having altered CSF marker levels, developed vascular dementia at follow-up." (PMID 32917274, 2020). "For patients carrying variants outside EGFr region, no potential pathogenic mutation were identified in several other genes known to be common causal of cerebral small-vessel disease or vascular dementia (HTRA1, TREX1, COL4A1, COL4A2, GLA, APP, and ITM2B) by targeted next-generation sequencing." (PMID 34335700, 2021).
amnesia (6 papers, 2008 to 2025). Pathologic partial or complete loss of the ability to recall past experiences ( AMNESIA, RETROGRADE) or to form new memories ( AMNESIA, ANTEROGRADE). "Some APP mutations had visuospatial and language impairments in addition to amnesia, while others had minor damage in these cognitive areas but showed more dyscalculia (e.g., V717I)." (PMID 36313020, 2022). "In the chick, APP is essential for memory consolidation, and disrupting its synthesis or structure results in amnesia." (PMID 20721285, 2010). "When injected pre-training, anti-APP did not interfere with the chicks pecking and learning the avoidance task; however, it did result in amnesia in birds tested 30 minutes later." (PMID 20721285, 2010). "Our data indicate that age-dependent remote memory impairment in APP/PS1 mice is due to increased innervation of cortical engram cells by hyperexcitable PV interneurons, suggesting that dysfunctional inhibitory microcircuits in the neocortex mediate progressive retrograde amnesia in AD." (PMID 41269883, 2025). "Hence, whereas initially only recent memory is affected in APP/PS1 mice, i.e., mimicking early temporally graded retrograde amnesia in patients, remote memory can no longer be retrieved at a later age, resembling the more severe retrograde amnesia, as observed in late-stage AD patients." (PMID 41269883, 2025).
cerebral (6 papers, 2010 to 2025). "Our RNA sequencing, IHC, and Western blot findings all support the idea that activated astrocytes play a key role in the loss of functional hyperemia, transient ischemia, cerebral inflammation, and loss of cognitive function in the APP/PS1 TgF344-AD rats." (PMID 40141075, 2025). "We report an association of cerebral amyloid metabolism with LNB, with decreased CSF levels of soluble APP-fragments in the acute disease stage." (PMID 20569437, 2010).
cerebral small vessel disease (6 papers, 2020 to 2025). Cerebral small vessel disease is the term currently used to pathological processes that affect the brain parenchymal circulation (arterioles, capillaries, and veins). "Of note, in another cerebral small vessel disease, Dutch-type hereditary cerebral amyloid angiopathy (D-CAA) that is caused by a single point mutation (E693Q) in the amyloid precursor protein (APP) gene, there also is an increased prevalence of migraine with aura." (PMID 32503413, 2020). "To test our hypotheses, we used a transgenic rat model that expresses APP and PS1 mutations but also has cerebral small vessel disease (chronic hypertension-driven cerebrovascular small vessel disease, a prevalent co-morbidity, that accelerates tauopathy in the model)." (PMID 40890882, 2025).
HIV-1 infection (6 papers, 2015 to 2026). The type species of lentivirus and the etiologic agent of acquired immunodeficiency syndrome (AIDS). "Here, we extend upon our previous discovery that APP is a highly expressed membrane protein in macrophages and microglia that limits HIV-1 infection and provide insights into the underlying mechanisms of both APP-mediated restriction and viral evasion." (PMID 37454116, 2023). "Notably, the top neuronal upstream regulator genes activated by HIV-1 infection in the AD context included APP, presenilin-1, microtubule-associated protein tau (MAPT), and mammalian target of rapamycin (mTOR)." (PMID 40313365, 2025). "This review will focus on recent advances in understanding the antiviral role of APP and its processing during HIV-1 infection, highlighting how APP-mediated defense mechanisms intersect with neurotoxic pathways and the intercellular regulatory networks that link APP to HAND." (PMID 42012178, 2026). "To explore this further, we first determined whether HIV-1 infection broadly overlaps with and affects APP sorting pathways by infecting CHME3 cells with either pNL4.3- or JR-CSF-derived HIV-1." (PMID 37454116, 2023). "Our findings explain how and why infection leads to Aβ production and its contribution to neuronal damage, revealing an antiviral activity of APP that could potentially be exploited to treat both HIV-1 infection and neurodegeneration." (PMID 29142315, 2017). "This suggested that protecting APP and CTFs from processing suppressed HIV-1 infection." (PMID 29142315, 2017). "Here we reveal that APP is highly expressed in macrophages and microglia, natural target cells for HIV-1 infection in the brain, and acts as an innate restriction factor that sequesters the HIV-1 Gag polyprotein in lipid rafts to block virus production and spread." (PMID 29142315, 2017). "Apart from inducing immune dysfunction, HIV-1 infection affects neuronal function by significantly increasing several cellular proteins in the brain, including amyloid precursor protein (APP), especially in the axons present in the subcortical white matter tracts." (PMID 26793166, 2015). "Immunofluorescence (IF) analysis of transfected cells also showed that APP co-localized with HIV-1 Gag in 293T cells and CHME3, a human microglia cell line and natural target cell type for HIV-1 infection in the brain." (PMID 29142315, 2017). "Specifically, we find that HIV-1 infection does not affect the turnover of the non-amyloidogenic APP product, C83." (PMID 37454116, 2023). "The fact that CTFs do not accumulate despite increased upstream cleavage of APP demonstrates that HIV-1 infection or HIV-1 Gag alone accelerate the entire pathway, and not just APP cleavage alone." (PMID 37454116, 2023). "While our data established that HIV-1 infection or Gag expression accelerated vesicle- and γ-secretase-based processing of APP and its CTFs, available antibodies do not reliably distinguish between C99 or C83 given their high degree of homology." (PMID 37454116, 2023). "This suggested that high levels of APP expression in macrophages and microglia, natural target cell types for HIV-1 infection, and its interaction with Gag could be of particular biological significance during HIV-1 infection in the brain." (PMID 29142315, 2017). "Instead, the negative effects of APP on HIV-1 infection appear to center around its vesicle-based amyloidogenic processing into the larger CTF, C99 that is ubiquitinated to control its intracellular sorting." (PMID 37454116, 2023). "For example, similar to our findings relating to the specific functionality of C99 in restricting HIV-1 infection, increased expression of APP or C99, but not C83, impairs endocytic sorting and retrograde axonal trafficking, resulting in neurodegeneration." (PMID 37454116, 2023).
injury (6 papers, 2011 to 2024). Damage inflicted on the body as the direct or indirect result of an external force, with or without disruption of structural continuity. "That APP is important for normal brain function was shown in studies in APP knockout mice where intracerebroventricular (ICV) injection of sAPPα can increase brain repair after traumatic brain injury." (PMID 34061681, 2021). "Thus, our finding that intra-axonal Aβ was detected starting at 1 hour post TBI in 3xTg-AD mice is in line with the reported time for the earliest APP accumulation following brain trauma." (PMID 21980472, 2011). "Consistent with earlier studies, the increased APP, GFAP and BMX metabolites are observed following brain injury using similar Marmarou acceleration weight drop model or other experimental TBI models, such as controlled cortical impact or fluid percussion models of brain injury." (PMID 28552947, 2017). "In any case, we can speculate that brain trauma did not modulate TNF-α in APP mice, at least at this presymptomatic stage." (PMID 38992700, 2024). "On the other hand, we found that brain trauma did not induce significant changes in APP-SWE mice." (PMID 38992700, 2024).
leukemia (6 papers, 2008 to 2024). A malignant (clonal) hematologic disorder, involving hematopoietic stem cells and characterized by the presence of primitive or atypical myeloid or lymphoid cells in the bone marrow and the blood. "The remaining third includes four genes conserved in nematodes, fly, mouse, and human (zfp-1, R11F4.1, apl-1 and fcd-2) and whose human homologs are linked to disorders (AF10/MLLT10: leukemia, Glycerol kinase: hyperglycerolemia, APP: Alzheimer's, and FANCD2: Fanconi anemia)." (PMID 18752680, 2008). "For example, nilotinib, an FDA-approved drug for leukemia, induced autophagy via mTOR inhibition, and reduced amyloid plaques and improved cognition in AD model Tg-APP mice." (PMID 39454957, 2024). "Researches have revealed that APP as a novel clue was involved in leukemia cell proliferation, extramedullary infiltration, and prognosis in AML." (PMID 33299888, 2020).
liver fibrosis (6 papers, 2021 to 2025). "Recently, Amyloid beta (Aβ) and associated amyloid precursor protein (APP) were found to protect against liver fibrosis." (PMID 40109726, 2025). "Specifically, studies have demonstrated that APP can inhibit hepatic stellate cell activation and reduce extracellular matrix deposition, thereby mitigating liver fibrosis." (PMID 41230834, 2025). "APP regulates mitochondrial function, lipid metabolism, and cell–cell interactions in a healthy liver, protecting against liver fibrosis." (PMID 40109726, 2025). "Consistent with our previous findings, low Aβ-42 levels in patients with liver fibrosis appear to be caused by the reduced production and enhanced non-amyloidogenic processing of APP." (PMID 39201455, 2024). "Based on the high expression of APP in BA liver biopsies with advanced fibrosis, we hypothesize that APP may be a driver of fibrogenesis offering potential as a predictive biomarker for progressive liver fibrosis." (PMID 39341941, 2025). "Our data also suggest that during liver fibrosis cleavage activities of γ‐secretase strongly favor the activation of NOTCH rather than cleaving APP to produce Aβ." (PMID 38430535, 2024).
nasopharyngeal carcinoma (6 papers, 2013 to 2025). A carcinoma arising from the nasopharyngeal epithelium. "The expression of APP is upregulated in nasopharyngeal carcinoma tissues, and this gene is also involved in the metastasis and invasion of nasopharyngeal carcinoma." (PMID 39012409, 2024). "In one study, APP knockdown inhibited the invasion and migration of human nasopharyngeal carcinoma cell line (SUNE-1) and increased the expressions of metastasis suppressor-related genes." (PMID 34066808, 2021). "In nasopharyngeal cancers, APP expression is regulated by epithelial growth factor receptor (EGFR) activation." (PMID 23662100, 2013). "APP is also involved in the invasion and migration of nasopharyngeal carcinoma cells." (PMID 34066808, 2021).
neuropathy (6 papers, 2022 to 2025). A disorder affecting the nervous system that manifests with pain, tingling, numbness, and/or muscle weakness. "It is worth mentioning that our conclusions are based on observations in two different animal models of Aβ-associated neuropathy (APP/PS1 and AppNL-G-F mice), and involved both microglia-selective as well as constitutive full body deletion of core inflammasome components (caspase-1 and Nlrp3)." (PMID 38352874, 2024). "Activation of the microglial Nlrp3 inflammasome has been proposed as a key contributor to the progression of AD pathology in the APP/PS1 and CRND8-APP models of Aβ-induced neuropathy." (PMID 38352874, 2024). "The number of healthy and surviving neurons in hippocampal CA1 and CA3 regions of 10-month-old APP/PS1 mice significantly reduced, that resulted in typical neuropathy, involving loss of Nissl body and nuclear disappearance in comparison to C57BL/6 mice." (PMID 36918872, 2023). "The accumulation of Aβ/APP-CTF promotes neuropathy by eliciting endosomal abnormality and Rab5 overactivation and compromising lysosomal calcium stores through inhibition of lysosome-ER contacts in PSEN1 knockout or mutant mouse neurons or human iNeurons45, 69–71." (PMID 37034684, 2025). "The accumulation of Aβ/APP-CTF promotes neuropathy by eliciting endosomal abnormality and Rab5 overactivation, and compromising lysosomal calcium stores through inhibition of lysosome–endoplasmic reticulum contacts in PSEN1-knockout or mutant mouse neurons, or human induced neurons." (PMID 40140603, 2025). "Among them, most brown neurofibrillary tangles appeared in the hippocampal tissues of APP/PS1 model mice, followed by Alu-Gal AD model mice, and least for Alu AD model mice, indicating that APP/PS1 model mice had the highest degree of neuropathy." (PMID 35846991, 2022). "Sustained transgenic overexpression of IL-1ß was shown to have a beneficial effect on amyloid burden without overt neurodegeneration in the APP/PS1 and APPswe/PS-1dE9 mouse models of Aβ-associated neuropathy." (PMID 38352874, 2024).
prediabetes (6 papers, 2018 to 2023). "For example, our group recently showed that APP/PSEN1 amyloid-depositing mice exhibit reduced hypothalamic insulin signaling and are more susceptible to aging and over-nutrition induced prediabetes." (PMID 29945658, 2018). "Our study employed classical models of prediabetes and T1D in APP/PS1 mice." (PMID 31992349, 2020). "The synergy between AD and T2D is supported at the preclinical level, with studies on both AD-prediabetes (APP/PS1 mice exposed to high fat diet) and AD-T2D models (APP/PS1xdb/db double transgenic mice)." (PMID 37817156, 2023). "We also observed that while amyloid plaque numbers were increased in prediabetes animals, plaque size was not significantly affected, as previously observed in APP/PS1 animals and this prediabetes model." (PMID 36345028, 2022).
sarcopenia (6 papers, 2018 to 2025). Progressive decline in muscle mass due to aging which results in decreased functional capacity of muscles. "For example, muscular Swedish mutant APP not only leads to sarcopenia-like deficits but also contributes to AD." (PMID 39654807, 2024). "In this review, we focused on Aβ, the cleavage product of APP, and comprehensively described the common pathological mechanism and targeted therapy of AD and sarcopenia." (PMID 39654807, 2024). "In the following, after a brief introduction to APP and its proteolytic cleavage product, we describe the effects and mechanisms of APP and its proteolytic cleavage product Aβ in sarcopenia and AD." (PMID 39654807, 2024). "Identification of the role of APP in muscles will also establish the link between sarcopenia and neurodegenerative diseases." (PMID 37175515, 2023). "In a cohort of old cattle showing signs of sarcopenia, age-related myopathic features reminiscent of sIBM, including Congo Red positive deposits and protein accumulations immunoreactive with anti-APP antibody 6E10 or anti-Mstn-C antibody, have been observed." (PMID 29546591, 2018). "Besides, it has also been found that, as the precursor of Aβ, APP’s high expression in skeletal muscle led to sarcopenia-like defects in AD mice, indicating the role of the axis of muscular APP to the brain in the development of AD." (PMID 40219034, 2025). "In summary, numerous studies indicate that Aβ, as the cleavage product of APP, plays a pivotal role in the biological mechanism of sarcopenia and AD comorbidity and may be a potential core intervention target for myocerebral comorbidity." (PMID 39654807, 2024). "Furthermore, studies in TgAPP swe HSA mice (a model with muscle-specific expression of APP swe) revealed sarcopenia-like muscle damage, age-related brain pathology, and behavioral abnormalities." (PMID 39654807, 2024). "Among these proteins, the abnormal expression of APP and the aggregation of its proteolytic cleavage product may play key roles, resulting in a series of physiological and biochemical reactions, eventually leading to the occurrence of sarcopenia." (PMID 39654807, 2024). "APP at the NMJ may be a key factor in the interplay between sarcopenia and AD." (PMID 39654807, 2024). "Therefore, in this review, we describe the current status of knowledge about sarcopenia and AD comorbidity, the physiological and pathological functions of APP cleavage products, and the potential role and mechanism of cleavage products in the development of sarcopenia and AD." (PMID 39654807, 2024). "Furthermore, AD and sarcopenia share some genetic risk factors, such as APOE and APP." (PMID 37175515, 2023). "Below, we summarized APP’s physiological functions in muscle and the NMJ and discussed mutant APP’s potential contributions to the development of sarcopenia and neurodegenerative diseases." (PMID 37175515, 2023).
bipolar disorder (5 papers, 2009 to 2021). A disorder of the brain that causes unusual shifts in mood, energy, activity levels and the ability to carry out day-to-day tasks. "The investigation about CSF amyloid and tau levels in bipolar patients showed altered APP metabolism also in bipolar disorder." (PMID 34679416, 2021). "Taken together, these previous studies suggested that altered APP metabolism and axonal injury might occur in bipolar disorder." (PMID 25954806, 2015). "In bipolar disorder, APP interacted with the abnormally expressed F12." (PMID 22373040, 2011).
brain inflammation (5 papers, 2017 to 2024). "However, the pathogenic role of beta-amyloid accumulation has been linked to a plethora of factors that are not necessarily linked with the functional roles of APP itself, such as brain inflammation, defective clearance, and alterations in the blood–brain barrier." (PMID 39355118, 2024).